TNF (tumor necrosis factor)
Diseases named in the same sentence as TNF in open-access papers (continued):
Sharing a sentence is not in itself a finding about the gene and the disease.
alveolitis (19 papers, 2009 to 2025). "Both MDA and TNF-α levels showed a remarkable elevation (p ˂ 0.05) in the allergic pneumonitis and CYP alone groups when compared to the control group." (PMID 37048067, 2023). "CYP exposure of the allergic pneumonitis (allergic/CYP) group caused a further significant increase (p ˂ 0.05) in the MDA and TNF-α measurements when compared to the allergic pneumonitis-only group." (PMID 37048067, 2023). "The four-time treatment of ASD alone (6-week study) caused bronchitis and alveolitis, and clearly increased neutrophils along with its relevant chemokines MIP-1α, KC (IL-8 in human) and other cytokines IL-12, TNF-α in BALF." (PMID 23731974, 2013). "The eight-time exposure of ASD alone (14-week study) deteriorated bronchitis and alveolitis, which accompanied with further increase of cytokines IL-1β, IL-6, IL-12, IL-17A and TNF-α; and chemokines KC, MIP-1α, and RANTES in BALF." (PMID 23731974, 2013). "It is indeed not well known if TNFα is sufficiently present in sarcoid lesions to play a relevant biological role despite the fact that its presence in BAL has been shown to correlate with the severity of alveolitis." (PMID 25866780, 2015). "One of them is that the two radiopharmaceuticals show different aspects of the same phenomenon: the intense [18F]-FDG uptake by the cell populations responsible of alveolitis (macrophages, lymphocytes, etc.)and the presence of TNFα revealed by radiolabelled 99mTc-infliximab." (PMID 25866780, 2015). "TNF-α promotes inflammatory cell recruitment through regulation of leukocyte and vascular adhesion molecule expression, while IL-6 has been shown to mitigate tissue inflammation in hypersensitivity pneumonitis and reduce lung injury from oxygen toxicity and endotoxin exposure." (PMID 41302046, 2025). "SPC-TNF transgenic mice, a variant generated by Dr. Vasalli in 1995, were used, and transgenic TNF on the SPC promoter was overexpressed only in lung tissue and consequently resulted in alveolitis, alveolar disruption, and subsequent fibrogenesis in lung tissue." (PMID 33466795, 2021). "Since BALF CD56+ T cells are efficient producers of IFN-γ and TNF-α, even more efficient than PB CD56+ T cells following stimulation, we assumed that BALF CD56+ T cells would contribute to the TH1 alveolitis." (PMID 34233893, 2021). "The r19FCX4C virus effectively reversed this increase with primary r19F infection as indicated by interstitial inflammation and alveolitis and levels of MX1, TNF-α, INF-g, and MCP-1 mRNA in lung tissue." (PMID 31330970, 2019). "Indeed, this herbal medicine can ameliorate pulmonary lesions as it downregulates alveolitis and the Ashcroft score, the underlying mechanism for this might relate to the downregulation of MPO, α-SMA, HYP, collagen I, collagen III, and inflammatory factors (TNF-α, IL-1β, and IL-6)." (PMID 34349830, 2021). "In patients with fibrotic hypersensitivity pneumonitis, ozanimod alleviated CD3/CD28 induction of CD69, IL-4, and TNF in CD8, but not CD4 T cells." (PMID 40243992, 2025).
aplastic anemia (19 papers, 2011 to 2024). Anemia resulting from bone marrow failure (aplastic or hypoplastic bone marrow). "In a mouse model of aplastic anemia induced by irradiation and spleen–thymus lymphocyte infusion, the levels of the cytokines IL-6, IL-8, IL-17, TNF-α, and IFN-γ were increased in peripheral blood and bone marrow, and an immunoinflammatory response occurred." (PMID 36976996, 2023). "TNF and IL6 are involved in the occurrence and development of chronic anaemia/IDA, and the level of TNF expression can reflect the degree of disease of patients with aplastic anaemia." (PMID 32345291, 2020). "Autoimmune response caused by activated T cells and hypersecretion of inflammatory cytokines like IFN-γ and TNF-α occupy the dominant position in the development of aplastic anemia." (PMID 31871547, 2019). "The levels of IFN-γ and TNF-α were increased significantly in bone marrow and peripheral blood of patients with aplastic anemia." (PMID 31818289, 2019). "Abnormalities of the levels of TNF-α and IL-6 have been proven playing important roles in the pathogenesis of aplastic anemia." (PMID 31871547, 2019). "Aberrant p38MAPK activity has been demonstrated in bone marrow-derived myeloid progenitors from patients with MDS or aplastic anemia, which has been explained by increased activity of the myelosuppressive cytokines IFNγ and TNFα, which stimulate p38MAPK activity." (PMID 24614182, 2014). "Similarly, IFN-γ and TNF-α expression is higher in the bone marrow of patients with aplastic anemia compared to healthy controls." (PMID 23882270, 2013). "As idiopathic aplastic anemia is associated with the increased level of secretion of INF-γ and TNF-α from T cells which inhibit the hematopoietic cell proliferation, similar increased level of serum INF-γ and TNF-α was found in the patient four weeks after the onset of aplastic anemia." (PMID 21352606, 2011). "However, it has been speculated that increased TNF-α levels may be responsible for the hematological manifestations of the disease, as TNF-α may have a role in bone marrow failure (BMF) in patients with aplastic anemia." (PMID 38357265, 2023). "Aplastic anemia (AA) is a BM failure syndrome characterized by hypoplasia of the BM and a decrease in whole blood cells in the peripheral blood, which are caused by an increase in interferon-γ (IFN-γ) and tumor necrosis factor-α (TNF-α), and a decrease in regulatory T cells (Tregs)." (PMID 37649079, 2023). "Interestingly, IFNγ and TNF-α have been described as possibly implicated in the pathophysiology of aplastic anemia and abnormal STAT1 activation was demonstrated in BM samples of few aplastic anemia patients." (PMID 35898506, 2022). "In a study of children with idiopathic aplastic anemia, bone marrow CD4+, and CD8+ cells expressing IFN-γ and TNF-α were significantly increased compared to normal controls, and a higher percentage of marrow TNF-α-expressing T cells correlated with an unfavorable outcome." (PMID 23882270, 2013).
Ascites (19 papers, 2007 to 2026). Accumulation of fluid in the peritoneal cavity (between the layers of the peritoneum that lines the abdomen). "OC-associated ascites showed an inhibitory effect on the production of the cytokines IL-6, IL-12p40 and TNFα in response to R848- and LPS-mediated activation." (PMID 28410380, 2017). "Unlike IL-10, PGE2 is absent from peritoneal fluid of patients with benign conditions and selectively reduces TNFα induction in response to TLR-mediated activation in the presence of OC-associated ascites." (PMID 28410380, 2017). "Accordingly, this study comprehensively explores the impacts of intestinal SIRT1 deficiency on TNFα-mediated intestinal inflammation, intestinal barrier dysfunction, intestinal bacterial dysbiosis, bacterial translocation on the development of severe renal dysfunction in cirrhotic mice with ascites." (PMID 33513830, 2021). "In cirrhotic rats with ascites, anti-TNFα monoclonal antibody administration directly suppresses intestinal inflammation, reduces intestinal barrier dysfunction, and decreases the incidence of bacterial translocation." (PMID 33513830, 2021). "Increased TNF-α level, along with hs-TnT levels in cirrhotic patients, especially higher values in patients with ascites, was observed in the present study." (PMID 26665009, 2015). "When the presence of ascites was considered, the plasma levels of AOPPs-albumin were higher, as well as TNF-α." (PMID 26665009, 2015). "It has also been demonstrated that cytokine blockade with anti-TNF-α monoclonal antibody can decrease the incidence of BT in cirrhotic rats with ascites, and the integrity of intestinal barrier can be preserved in the IL-6 knockout mice." (PMID 25171482, 2014). "To investigate whether PGE2 present in ascites inhibits TNFα induction, we neutralized PGE2 in cultures of cells stimulated with R848 in the presence of OC-associated ascites." (PMID 28410380, 2017). "Of note, bowel decontamination normalizes the frequencies of proinflammatory IFN-γ and TNF-α cytokines, the phagocytic activity of DCs, and gut permeability, as revealed by a reduction in fecal albumin loss and by fully suppressed GBT in cirrhotic rats with ascites." (PMID 37122743, 2023). "While IL-10 levels in OC-associated ascites correlated with a reduced induction of most DC activation markers in our study, IL-10 levels did not correlate with the suppression of TNFα production indicating the presence of at least one other immunosuppressive factor." (PMID 28410380, 2017). "Collectively, our data demonstrate that the progression of patients from outpatients with ascites to patients hospitalised with AD/ACLF is accompanied by an increase in bioavailable PGE2, reduced monocyte HLA-DR expression, and reduced monocyte TNFα/IL6 production." (PMID 34825153, 2021). "The median TNF-α levels were higher in CHC patients with ascites than patients without ascites (55.0 pg/mL versus 32.3 pg/mL, P < 0.01)." (PMID 26665009, 2015). "The association between dietary fiber intake and interleukin (IL)-1β, IL-6, tumor necrosis factor-α (TNF-α), monocyte chemoattractant protein-1 (MCP-1), B-cell activating factor (BAFF), and plasminogen activator inhibitor-1 (PAI-1) levels in serum and peritoneal effusion." (PMID 40735439, 2025). "We conclude that levels of IL-10 found in OC-associated ascites positively correlate with the inhibitory properties of ascites on the TLR-mediated up-regulation of the co-stimulatory molecule CD86, as well as the production of the cytokines IL-6 and IL-12p40 but not TNFα." (PMID 28410380, 2017).
cerebral aneurysm (19 papers, 2012 to 2025). "TNF-α is a critical member of the immune system and produces pro-inflammatory alterations in key cells implicated in cerebral aneurysms including macrophages, endothelial and smooth muscle cells." (PMID 24739142, 2014). "Alterations in TNF-α expression have been associated with cerebral aneurysms, but a direct role in formation, progression, and rupture has not been established." (PMID 24739142, 2014). "Additional risk factors associated with cerebral aneurysms, including aging, gender, and alcohol, have also been associated with TNF-α expression." (PMID 24739142, 2014). "A number of environmental factors associated with cerebral aneurysm formation have been implicated in TNF-α activation." (PMID 24739142, 2014). "TNF-α is a key initiator of apoptosis and its pro-apoptotic protein target (Fas-associated death domain) have been increased in human cerebral aneurysms." (PMID 24739142, 2014). "We have previously found that TNF-α can activate a number of pro-inflammatory and matrix remodeling genes in cerebral vascular smooth muscle cells directly implicated in cerebral aneurysm formation, including: MMP-3, MMP-9, MCP-1, VCAM-1, and IL-1β; and IL-1β, VCAM-1 and MCP-1." (PMID 24739142, 2014). "PCA, in another study, attenuated cerebral aneurysm progression by blocking the activation of TNF-α/NF-κB/ IL-17 signaling pathways." (PMID 36877411, 2023). "Cerebral aneurysm formation and rupture were significantly reduced in MCP1-, TNF-α-, and TNF-α-R1 deficient mice." (PMID 37107335, 2023). "Sitosterol can treat cerebral aneurysms by reducing the expression of chemokines and inflammatory cytokines TNF-α, IL-8, IL-1β, IL-17, IL-6, and MMP-2/9." (PMID 33149752, 2020). "It is affirmed that TNF-α intermediates in inflammatory response resulting in the growth of cerebral aneurysm in humans." (PMID 32341986, 2019). "Primary aim of this trial is to determine the influence of local anesthesia with lidocaine on the perioperative levels of pro-inflammatory cytokines interleukin-1β, interleukin-6, and tumor necrosis factor-α in plasma and CSF in cerebral aneurysm patients." (PMID 31626100, 2019). "It is further established that, TNF-α does not only trigger inflammation but also stimulates the inflammatory cascade in response to cerebral aneurysm rupture resulting in SAH." (PMID 32341986, 2019). "Much like TBI, ruptured brain aneurysms also induce an influx of peripheral immune cell infiltration into the brain, and increases in IL1β, IL-6, MCP1, and TNF have been associated with poor outcomes for both." (PMID 31711546, 2019). "In this study we have found that the expression of the pro-inflammatory cytokine TNF-α is increased in a mouse model of cerebral aneurysms." (PMID 24739142, 2014). "TNF-α has also been found to be elevated in humans with ruptured cerebral aneurysms, but mechanisms behind TNF-α activation in cerebral aneurysms are currently unclear." (PMID 24739142, 2014). "Cerebral aneurysm formation occurred in 18 of 22 (81.8%) animals receiving only vehicle as compared to 3 of 12 TNF-α knockout mice (25%, P = 0.002) and 4 of 12 mice (33%, P = 0.008) treated with DTH." (PMID 24739142, 2014). "As alterations in TNF-α have been associated with human intracranial aneurysms, we sought to assess alterations in expression of TNF-α in this animal model of cerebral aneurysms." (PMID 24739142, 2014). "Additional experiments are indicated both in vivo and in humans to assess the role of TNF-α in cerebral aneurysm progression and rupture." (PMID 24739142, 2014). "In summary, we have demonstrated that TNF-α is increased in both unruptured and ruptured cerebral aneurysms in an in vivo model of cerebral aneurysm formation." (PMID 24739142, 2014). "Specifically, smokers have higher levels of IL-1β, TNFα, and IL-6, all of which significantly contribute to the pathobiology of cerebral aneurysm." (PMID 23316103, 2012).
cerebral aneurysm (continued). "Based on recent data, any relationship between SARS-CoV-2 infection and cerebral aneurysm rupture could possibly involve macrophage-mediated production of interleukin-1β, interleukin-6, and tumor necrosis factor-α." (PMID 35386414, 2022). "Previous studies showed the changes in TNF-α are related to human cerebral aneurysms." (PMID 35469231, 2022). "For example, protocatechuic acid impacts cerebral aneurysm through TNF-α/NF-κB/Nrf-2 signaling." (PMID 35196182, 2022). "Trial will test the hypothesis that lidocaine administration decreases concentrations of IL-1β, IL-6, and TNF-α in plasma and CSF in patients undergoing cerebral aneurysm surgery." (PMID 31626100, 2019). "Others reported that TNF-α modulates cerebral aneurysm formation and rupture." (PMID 28969701, 2017). "Additionally, 3,6′-dithiothalidomide has recently been described to lower TNF-α and cerebral aneurysm formation and progression to rupture in mice." (PMID 25879458, 2015). "Specifically, increased MCP-1 may attract macrophages leading to increased TNF-α formation, and macrophages have previously been found to be critical in the formation of cerebral aneurysms." (PMID 24739142, 2014). "Although there are likely many further key mediators, TNF-α may contribute to cerebral aneurysm formation through activation of pro-inflammatory and matrix remodeling genes and recruitment and activation of inflammatory cells." (PMID 24739142, 2014). "Likewise, TNFα was shown to induce apoptosis of VSMC in cerebral aneurysm walls while also activating MMP and vessel wall degradation." (PMID 23316103, 2012). "The incidence of cerebral aneurysm formation and rupture was decreased in TNF-α knockout mice and following pre-treatment with a synthesized TNF-α inhibitor." (PMID 24739142, 2014). "TNFα can also induce cerebral SMC phenotypic changes through KLF4 and Myocardin, which may contribute to cerebral aneurysm formation." (PMID 37686377, 2023). "Although the downstream mechanisms by which TNF-α contributes to cerebral aneurysm formation are not completely defined, inflammation is a significant element behind the pathogenesis of cerebral aneurysm formation, and TNF-α is a significant pro-inflammatory immune modulator." (PMID 24739142, 2014).
coccidioidomycosis (19 papers, 2007 to 2024). A fungal infection caused by Coccidioides immitis. "The first case series of coccidioidomycosis associated with targeted immunotherapy documented 13 patients using TNF inhibitor (TNFi) treatment for rheumatologic diagnosis." (PMID 38667927, 2024). "Cohort studies involving biologic therapies revealed that inhibition of TNF by monoclonal antibodies or soluble TNF receptors led to an increased risk of coccidioidomycosis." (PMID 38667927, 2024). "In the less than 1% of patients with Coccidioides infection who develop disseminated disease, exogenous immunosuppression is a major risk factor, as highlighted by the warnings for TNF-α biologics as a class." (PMID 36166305, 2022). "In endemic areas, patients treated with TNF inhibitors are at risk of developing coccidioidomycosis." (PMID 28146077, 2017). "A multi-center study of rheumatologic patients from coccidioidomycosis endemic regions also demonstrated increased risk of coccidioidomycosis in patients treated with TNF antagonists." (PMID 17803815, 2007). "In this study, 13 cases of coccidioidomycosis (12 associated with infliximab and 1 with etanercept) were identified among 918 patients being treated with TNF antagonist over a 5-year period." (PMID 17803815, 2007). "Mild coccidioidomycosis in patients who have comorbidities that increase their risk of prolonged infection (e.g., TNF inhibitors, chemotherapy, solid organ transplant) may necessitate the use of antifungal medications." (PMID 36675936, 2023). "A recent meta-analysis of the anti-TNF antibody agents infiximab and adalumimab in 3493 patients with rheumatoid arthritis demonstrated increased risk of serious infections in 126 patients but only 1 case of coccidioidomycosis." (PMID 17803815, 2007). "Dogs with coccidioidomycosis produced higher coccidioidal stimulated supernatant concentrations of TNF-α (p = 0.003), IL-6 (p = 0.04), IFN-γ (p = 0.03), MCP-1 (p = 0.02), IL-10 (p = 0.02), and lower IL-8 (p = 0.003) than controls." (PMID 36836327, 2023). "Ampel demonstrated that PBMCs from humans with coccidioidomycosis produced lower concentrations of TNF-α when TLR2 and TLR4 were blocked with antibody during stimulation with the coccidioidal extract, T27K, a complex glycoprotein antigen mixture." (PMID 36836327, 2023). "The need to understand TNFα in Coccidioides infection has increased recently with the widespread use of TNFα inhibitors for a wide variety of autoimmune conditions." (PMID 35174101, 2021). "Mice treated with anti-TNFα showed an increased fungal burden in the lungs and spleen compared to control-treated animals (p = 0.0015, p = 0.0062), highlighting a role for TNFα in the long-term maintenance of Coccidioides infection in B6D2F1 mice." (PMID 35174101, 2021). "Together, these data show a role for TNFα not only in establishing control but also in long-term control of the Coccidioides infection, particularly in relation to disseminated disease." (PMID 35174101, 2021). "They induced higher proliferation of lymphocytes from both active and treated groups in comparison with the controls, and with gp43-stimulated moDCs, also upregulating IFN-γ and TNF-α, corroborating results obtained in coccidioidomycosis." (PMID 33802081, 2021). "Coupled together, these insights led to a model for testing the effect of TNFα BRMs on Coccidioides infection as described here." (PMID 35174101, 2021). "Tumor necrosis factor alpha (TNFα) is a pluripotent cytokine that is important in many infections, though its role in Coccidioides infection remains poorly understood." (PMID 35174101, 2021). "When diagnosed, invasive pulmonary coccidioidomycosis should be treated with fluconazole at the dose of 400–800 mg/day for 3–6 months, and anti-TNF therapy should be discontinued." (PMID 28146077, 2017). "We describe a case of fatal miliary coccidioidomycosis in a 78 year old white man taking the anti-TNF agent infliximab." (PMID 17803815, 2007).